IL6 (interleukin 6)
Diseases named in the same sentence as IL6 in open-access papers (continued):
Sharing a sentence is not in itself a finding about the gene and the disease.
metastatic colorectal cancer (8 papers, 2015 to 2023). "Similarly, a flattened cortisol slope has been associated with higher circulating levels of plasma IL-6 in epithelial ovarian cancer and metastatic colorectal cancer." (PMID 26305622, 2015). "Recently our group demonstrated that higher levels of IL-6 and CXCL10 were significantly associated with poor disease-free survival in metastatic colorectal cancer (mCRC) patients treated with bevacizumab plus oxaliplatin-based regimens." (PMID 36902351, 2023). "The inflammatory biomarkers, YKL-40 and interleukin-6 (IL-6), are elevated in patients with metastatic colorectal cancer." (PMID 32756596, 2020). "They assessed the effect of IL-6 on outcome and the response to therapy in patients with advanced or metastatic colorectal cancer treated with chemotherapy or chemotherapy and bevacizumab combined." (PMID 30038723, 2018). "A significant correlation was observed between serum levels of TGF-A and IL-6, circadian patterns and serum cortisol in patients with metastatic colorectal cancer." (PMID 26208480, 2015). "The aim was to explore the prognostic significance of IL-6 and markers of systemic inflammatory response (SIR), in particular C-reactive protein (CRP), in metastatic colorectal cancer (mCRC) patients, in the total study population and according to RAS and BRAF mutation status." (PMID 27738330, 2016).
narcolepsy (8 papers, 2014 to 2024). A sleep disorder characterized by a tendency for excessive sleepiness during the day which occurs even after adequate sleep in the nighttime. "Higher plasma IL-6 levels correlated with greater sleepiness, as measured by mean sleep latency during naps in narcolepsy, hypersomnia, and OSA patients." (PMID 35898322, 2022).
neovascular glaucoma (8 papers, 2010 to 2024). "In our study, patients with neovascular glaucoma that was refractory to treatment showed higher levels of IL-6, TGFβ-1, and VEGF than other PDR patients, which implies that the levels of these three factors are correlated with the severity of PDR." (PMID 26491551, 2015). "Patients in group 3 (those with neovascular glaucoma that was refractory to treatment) had higher levels of IL-6, TGFβ-1, and VEGF compared with patients in PDR group 1 and PDR group 2 (the nonneovascular glaucoma groups)." (PMID 26491551, 2015). "Another theory suggests that an increase in vascular permeability factors, including vascular endothelial growth factor and interleukin-6, promote the development of neovascular glaucoma." (PMID 25268829, 2014). "In addition, different inflammatory molecules, including interleukin (IL)-6, IL-8, platelet-derived growth factor, and interferon-α (among others), have been involved in the onset of neovascular glaucoma." (PMID 39678032, 2024). "Their results reinforce these findings and also suggest that, in patients with neovascular glaucoma refractory to treatment, IL-6 and TGF-β1 may have a potential use in patient stratification and in determining personalized medical needs." (PMID 26491556, 2015). "Also, in aqueous humour of patients with neovascular glaucoma, increased concentration of IL-6 correlated with the severity of iris neovascularisation." (PMID 20467456, 2010). "Also, in the neovascular glaucoma (NVG) patients, increased level of IL-6, IL-8, PDGF, CCL2, and TNF-α in AH were previously reported." (PMID 32117217, 2020).
orchitis (8 papers, 2015 to 2025). Inflammation of one or both testes due to viral or bacterial infections. "In a model of orchitis induced by LPS in bovine Sertoli cells, LPS induced IL-6 and IL-1 β, and downregulated the expression of ZO-1 and occludin, resulting in the inflammatory response of Sertoli cells and TJ damage." (PMID 37376572, 2023). "IMD can inhibit the gene expression of the proinflammatory cytokines (TNF-α, IL-6, and IL-1β) in LPS-induced rat testis inflammation." (PMID 34434487, 2021). "In addition, exosomes isolated using a mouse model of UPEC-induced orchitis promoted macrophage M1 activation and consequently increased the levels of proinflammatory cytokines (e.g., TNFα, IL-1β, and IL-6) in the testes." (PMID 38190378, 2024). "Animals subjected to LPS were found to have severe orchitis, as evidenced by increased oxidative stress and surging inflammatory mediators (TNF-α, IL-1β, and IL-6), with declined IL-10 levels." (PMID 39845795, 2024). "In a rat model of testis inflammation, ADM2 treatment protected against LPS-induced damage by decreasing the levels of reactive oxygen species, TNF-α, IL-6, and IL-1 ß." (PMID 26485688, 2015). "Lipopolysaccharides (LPS) is a key element of the external membrane found in Gram-negative bacteria and can cause orchitis by promoting the production of ROS and inflammatory mediators such as TNF-α, IL-6, and IL-1β in testicular tissue." (PMID 39845795, 2024). "Orchitis may be induced by discrepancies in the inflammatory and anti-inflammatory cytokine levels in testicular cells, including TNF-α, interleukin (IL)-1β, (IL-6), and IL-10." (PMID 39845795, 2024).
otitis media (8 papers, 2011 to 2025). Inflammation of the anatomical structures of the middle ear, which is most often caused by an infectious process. "Pro-inflammatory cytokines like IL-1β and IL-6 have a significant involvement in otitis media development and its progression." (PMID 40895301, 2025). "Previous candidate gene studies associated a number of immune system genes with otitis media, which included TNF-α, IL-6, IL-10, Tlr4, surfactant, CD14, FcγRIIa, IFNγ, Eya4, p73, MyD88, Fas, E2f4, Plg, Fbxo11, and Evi1." (PMID 24466073, 2014). "This indicated that the TNF-α, IL-1β, IL-6, IL-8 and IL-10 involved into inflammatory response in otitis media." (PMID 22173336, 2011). "Studies have found that the concentration of IL-6 in the ear cavity effusion of patients with CSOM is markedly higher than that in patients with other types of otitis media, indicating that IL-6 may play a pivotal role in the onset and progression of CSOM18." (PMID 41258032, 2025). "In this study, using a model that causes otitis media (OM), a disease with a high incidence in children, we confirmed the efficacy of MSC-derived EV to reduce inflammatory factors (TNF-, COX-2, IL-1, and IL-6)." (PMID 34016123, 2021). "However, Leffers, in his article on the immunomodulatory response of epithelial cells in otitis media, evaluated the immunohistochemical changes that occur in the epithelium after inoculation with Haemophilus influenzae, finding an increase in IL-1β, IL-6, IL-8, and TNFα." (PMID 40559231, 2025). "In vivo experiments utilizing a rat model of otitis media demonstrated a significant reduction in the levels of pro-inflammatory cytokines TNF-α, IL-1β, TLR4, and IL-6, and greater levels of Nrf-2 and SOD in comparison to untreated controls." (PMID 40143156, 2025). "A histopathological analysis confirmed that treatment with the nanocarriers reduced the levels of pro-inflammatory cytokines (IL-1β, TNF-α, TLR4, IL-6) and raised the levels of antioxidant markers (Nrf-2, SOD) in an in vivo rat model of otitis media." (PMID 40143156, 2025).
ovarian dysfunction (8 papers, 2021 to 2025). The inability of the ovaries to function. "While IL-6 plays a dual role (both pro- and anti-inflammatory), IL-18 is predominantly pro-inflammatory and directly exacerbates metabolic and ovarian dysfunction." (PMID 40385768, 2025). "Elevated IL-6 can enhance the secretion of other inflammatory cytokines and chemokines, creating a vicious cycle of inflammation that perpetuates ovarian dysfunction." (PMID 39691364, 2024). "In summary, our findings offer a mechanistic explanation for PM2.5-induced ovarian dysfunction and verify IL-6 as a biomarker and potential therapeutic target." (PMID 39639885, 2024). "Neutralizing IL-6 (with tocilizumab) may mitigate inflammation-driven endometrial damage and ovarian dysfunction." (PMID 41227338, 2025). "Compared to IL-6 and TNF-α, which primarily mediate systemic inflammation, VEGF is more directly involved in ovarian dysfunction and vascular abnormalities in PCOS." (PMID 40385768, 2025).
pharyngitis (8 papers, 2020 to 2025). Inflammation of the throat most often caused by viral and bacterial infections. "Individuals suffering from pharyngitis exhibited elevated levels of salivary pro-inflammatory cytokines, namely IL-1Ra, Interleukin-6 (IL-6), IFNγ, and IP-10." (PMID 40276383, 2025). "Many traditional Chinese medicine formulations exert their therapeutic effects in treating pharyngitis by suppressing the release of inflammatory factors, including IL-6, IL-1β, PGE2, and TNF-α, etc." (PMID 39568590, 2024). "Moreover, Gancao Jiegeng Shegan Decoction can regulate the levels of cyclooxygenase-2 and PGE2; reduce the serum TNF-α, IL-1β, and IL-6 levels; reduce throat inflammation; and exert expectorant effects." (PMID 38464723, 2024). "Animal experiments showed that CQQN could significantly reduce the expression of TNF-α, IL-1β, IL-6, and IL-17 in the serum of rats with pharyngitis (P < 0.05)." (PMID 35528163, 2022). "The inhibition of YHQ on TNF-α and IL-6 implied that alleviation of YHQ on pharyngitis may depend on down-regulation of inflammatory mediators." (PMID 32928206, 2020). "In pharyngitis, KHJ reduced pathological damage, downregulated interleukin 1β (IL-1β), interleukin 6 (IL-6), prostaglandin E2 (PGE2), and elevated interleukin 10 (IL-10)." (PMID 41357871, 2025). "Nevertheless, these outcomes recommend that the inhibitory effects of YHQ on 5-LOX/LT-B4/LT-D4 and COX-2/PGE2 are consistent with its inhibitory effects on pro-inflammatory cytokines (IL-6 and TNF-α) in ammonia-induced pharyngitis." (PMID 32928206, 2020). "Protein expressions of MAPKs, NF-κB, COX-2 and 5-LOX in pharyngitis tissue were evaluated by western blot analysis and the levels of TNF-α, IL-6, prostaglandin (PG) E2, leukotrienes (LT)-B4 and LT-D4 in pharyngeal tissue were measured via ELISA assay." (PMID 32928206, 2020).
pituitary adenomas (8 papers, 2012 to 2024). "Plasma fibrinogen is linked to the interleukin-6 (IL-6) gene promoter and is induced by the autocrine functioning of pituitary adenoma cells." (PMID 36498723, 2022). "It is also notable that estradiol stimulates VEGF and interleukin-6 in human lactotroph and lactosomatotroph pituitary adenomas." (PMID 25778675, 2015). "In the current study, it was demonstrated that the reduced expression of IL6 and STAT3 was associated with pituitary adenoma immune abnormalities." (PMID 25360166, 2014). "In pituitary adenoma cultures, cells other than FS cells are responsible for IL-6 production." (PMID 27902467, 2017). "The production of IL-6 in the normal pituitary gland was hypothesized to be secreted by FS cells; however, in pituitary adenomas, the source of IL-6 is the tumor cells." (PMID 25360166, 2014). "Paracrine IL-6 may be a condition that permits the growth of pituitary cells by contributes to excessive hormone production, growth, and neovascularization of pituitary adenomas, while autocrine IL-6 inhibits the aggressive growth and malignant transformation of tumors." (PMID 34090476, 2021). "In summary, IL‐6, CCL2, EGF/EGFR, VEGF/VEGFR, and other cytokines are expressed in pituitary adenomas and are generally related to their aggressiveness, occurrence, and development." (PMID 38738958, 2024). "A study involving 40 cases each of invasive pituitary adenoma (IPA) and non-invasive pituitary adenoma (NIPA) used the streptavidin peroxidase immunohistochemical method to examine TNF-α and IL-6 expression." (PMID 38275385, 2023). "As the results in module one demonstrated, the direct combined action and coadjustment between IL-6 and STAT3 was observed on pituitary adenoma development." (PMID 25360166, 2014). "BCL6 is essential in pituitary adenoma due to interactions with several factors, including STAT3, IL-6 and JUNB." (PMID 25360166, 2014). "The low expression of IL-6 and STAT3 was important in the dysimmunity of the pituitary adenoma." (PMID 25360166, 2014). "Low expression levels of IL-6 and STAT3 were significant in the dysimmunity of pituitary adenoma." (PMID 25360166, 2014).
premalignant oral lesions (8 papers, 2014 to 2024). "Studies of premalignant oral lesions in patients and in a murine oral model of premalignant oral lesions have shown an increased inflammatory state that is characterized by increases in levels of inflammatory cytokines such as IL-6, TNF-α and IL-17." (PMID 27453801, 2016). "Compared to healthy controls, patients with premalignant oral lesions had increases in their systemic levels of the inflammatory cytokines IL-6 and IL-17, and increases in the adipokine, leptin." (PMID 26120967, 2015). "In addition to OSCC, salivary IL-6 protein concentration was investigated in oral premalignant lesions (OPML)." (PMID 31766212, 2019). "The present study also showed increased serum levels of pro-inflammatory cytokines IL-6 and IL-17, and in levels of leptin in patients with premalignant oral lesions or in HNSCC patients treated with 1,25(OH)2D3, which is inverse to what is seen for adiponectin." (PMID 26120967, 2015). "Levels of IL-2 and IFN-γ were not increased in the peripheral blood of patients with either premalignant oral lesions or HNSCC, although levels of IL-6 and IL-17 were increased in the plasma of patients with premalignant oral lesions as compared to control patients." (PMID 25419481, 2014). "The results showed a dependence on IL-23 signaling for the pro-inflammatory state of mice with oral lesions as levels of IL-2, IFN-γ, IL-6, IL-17 and TNF-α were elevated in wildtype mice with premalignant oral lesions, but not in IL-23R KO mice." (PMID 29664967, 2018).
Senile plaques (8 papers, 2015 to 2024). Senile plaques are extracellular deposits of amyloid in the gray matter of the brain. "Most of these accumulated astrocytes express the age-related secretory factor interleukin-6 (IL-6), suggesting that astrocytes clustered around senile plaques possess aging characteristics." (PMID 37815901, 2024). "AD cortical senile plaques display strong IL-6 immunoreactivity, which is functionally related to alpha-2-macroglobulin." (PMID 36936500, 2023). "Moreover, in AD patients, IL-6 is present in senile plaques, and raised immunoreactivity to IL-6 is noticed in ventricular and lumbar cerebrospinal fluid." (PMID 33747345, 2021). "Moreover, overproduced IL-6 accumulates around and inside senile plaques in the cerebral cortex and hippocampi of AD patients." (PMID 32498476, 2020). "In the brains of AD patients, microglial activation is observed in the vicinity of senile plaques at all stages of the disease and is accompanied by increased levels of proinflammatory molecules (e.g., TNF, IL-1β, IL-6, prostaglandins)." (PMID 34228639, 2021). "Increased numbers of activated microglia and elevated levels of IL-6 mRNA have also been found in the hippocampus of patients with dementia with Lewy bodies (DLB), a neurodegenerative dementia disorder characterised by the presence of both senile plaques and α-synuclein occlusions." (PMID 26434635, 2015).
Skin rash (8 papers, 2014 to 2024). A red eruption of the skin. "Some potential biomarkers of toxicity during TKI therapy include circulating cytokines, such as IL-6 and TNF-alpha, which have been associated with inflammatory side effects like skin rashes, gastrointestinal disturbances, and fatigue." (PMID 39882443, 2024). "As a proinflammatory cytokine, IL-6 may be responsible for fever and skin rash, as well as the production of acute-phase proteins in AOSD." (PMID 34239943, 2021).
thyroid-associated ophthalmopathy (8 papers, 2010 to 2025). "We also examined mucosal expression of IL-6, which stimulates excess GAG synthesis in disorders such as Grave's ophthalmopathy." (PMID 25198673, 2014).
Tinnitus (8 papers, 2020 to 2025). Tinnitus is an auditory perception that can be described as the experience of sound, in the ear or in the head, in the absence of external acoustic stimulation. "Activated platelets release cytokines like IL-6, IL-8, and TNF-α within minutes, potentially contributing to prothrombotic conditions or thrombotic events in the internal auditory artery, leading to cochlear hypoperfusion and tinnitus." (PMID 40697272, 2025). "Furthermore, CoQ10 possesses anti-inflammatory properties, which may help reduce inflammation by targeting pro-inflammatory cytokines like IL-6 and TNF-α, potentially contributing to the alleviation of tinnitus symptoms." (PMID 39850225, 2025). "Additionally, emerging evidence suggests that neuroinflammation may play a large role in the development of tinnitus and the influence of various proinflammatory cytokines such as TNF-α, IL-6, β-2GP1 and IL-1 has been described." (PMID 38327985, 2024). "The core components of Liuwei Dihuang Pill in the treatment of tinnitus including quercetin, stigmasterol, kaempferol, β-sitosterol, tetrahydroalstonine, which may act on core targets such as STAT3, transcription factor AP-1 (JUN), tumor necrosis factor (TNF), interleukin-6 and MAPK3." (PMID 36401375, 2022). "In chronic tinnitus sufferers, a relaxation training program can result in significantly decreased stress, anxious depression, anger, and tinnitus disturbance, paralleled by a reduction of TNF-a, but not IL-6 or IL-10." (PMID 38027533, 2023).
acute leukemia (7 papers, 2013 to 2024). A clonal (malignant) hematopoietic disorder with an acute onset, affecting the bone marrow and the peripheral blood. "Survivors of childhood acute leukemia had increased levels of leptin and interleukin-6 (IL-6) and had higher percent fat mass despite similar BMI as controls." (PMID 35135482, 2022). "At the time of malignancy diagnosis, plasma from patients with acute leukemia displayed higher concentrations (P<0.05) of IL-6, IL-8, IL-10, and TNF-α and lower levels of pro-LL-37 (P<0.001)." (PMID 23741421, 2013). "The plasma from patients with acute leukemia displayed significantly higher concentrations of both pro-inflammatory cytokines (IL-6, IL-8, and TNF-α) and the anti-inflammatory cytokine (IL-10)." (PMID 23741421, 2013). "Other authors have observed an increase in proinflammatory cytokines like IL6 in mouse models of acute leukemia treated with OOS, suggesting that the macrophage-polarization effect of OOS could be extended to other cancers." (PMID 31467641, 2019). "In human acute leukemia cells (HTP-1), curcumin reduces the production of the cytokines IL-6 and TNF-α induced by Aβ protein and inhibits the phosphorylation of mitogen-activated protein kinase (MAPK) and extracellular regulated protein kinase 1/2 (ERK1/2)." (PMID 33489032, 2020).